NINJ1 (ninjurin 1)
Diseases named in the same sentence as NINJ1 in open-access papers (continued):
Sharing a sentence is not in itself a finding about the gene and the disease.
infection (continued). "Infection with two other IAV strains yielded similar results, indicating that the impact of NINJ1 on IL-1β release is not strain specific but rather a universal phenomenon." (PMID 40983621, 2025). "NINJ1 blocks HSV-1 entry into mouse macrophages independent of its role in cell death, resulting in greater secretion of pro inflammatory cytokines downstream of infection." (PMID 41261285, 2026). "NINJ1 blocks HSV-1 entry into mouse macrophages independent of its role in cell death, resulting in greater expression of pro inflammatory cytokines downstream of infection." (PMID 41261285, 2026). "Finally, we broaden our perspective from infection to other non-infectious but equally PMR-driven major diseases, and systematically evaluate the commonalities and prospects of NINJ1-targeted therapeutic strategies across different pathological scenarios." (PMID 42196375, 2026).
cancer (13 papers, 2020 to 2026). A tumor composed of atypical neoplastic, often pleomorphic cells that invade other tissues. "NINJ1 expression is induced in response to various stresses within the tumor microenvironment and it plays an important role in macrophage-mediated inflammation and vascular remodeling, both of which are closely associated with cancer development and progression." (PMID 39958360, 2025). "Additionally, the association between NINJ1 and the xCT transporter, along with its impact on GSH and CoA availability, provides insight into a potential mechanism underlying the tumor-suppressive role of NINJ1 in certain cancer types that depend on xCT-mediated metabolic pathways." (PMID 40075648, 2025). "Furthermore, the association between NINJ1 and the xCT transporter, along with the availability of GSH and CoA, could also imply a potential mechanism underlying the tumor suppression function of NINJ1 in certain cancer types." (PMID 39424803, 2024). "This revised understanding calls for a systematic integration of previous observations, particularly given NINJ1's context-dependent and often contradictory roles in inflammation, cancer, and tissue injury." (PMID 41888126, 2026). "Specifically, NINJ1 knockdown significantly protected cancer cells from ferroptosis induced by class I FINs (xCT inhibitors) but not by other FINs." (PMID 40075648, 2025). "Understanding how NINJ1 can either promote or suppress ferroptosis, depending on the cancer type, opens possibilities for novel treatments, particularly for preventing metastasis and targeting treatment-resistant cells." (PMID 40075648, 2025). "Extensive research highlights the multifaceted role of NINJ1 in cancer biology, with evidence suggesting both tumor-promoting and tumor-suppressing functions." (PMID 40075648, 2025). "Given that ferroptosis has been associated with tumor suppression, metastasis, the elimination of treatment-resistant cancer cells, and tumor dormancy, NINJ1′s modulation of ferroptosis presents a promising therapeutic target for inhibiting metastasis." (PMID 40075648, 2025). "Given the diverse roles of NINJ1 in cancer biology and ferroptosis, manipulating NINJ1 presents a promising strategy for cancer therapy by simultaneously modulating ferroptosis and tumor invasion." (PMID 40075648, 2025). "The review also discusses the context- and cell type-dependent functions of NINJ1 in various cancer types." (PMID 40075648, 2025). "Owing to its adhesion properties, NINJ1 also plays an important role in inflammatory diseases, cancer, and vascular injuries." (PMID 39958360, 2025). "Subsequent studies have uncovered its participation in cancer progression, where NINJ1 regulates critical steps in tumor metastasis, such as cell migration and invasion." (PMID 40075648, 2025). "This regulatory role positions NINJ1 as a potential therapeutic target for selectively enhancing ferroptosis sensitivity in cancer cells, especially those reliant on xCT-mediated metabolic pathways." (PMID 40075648, 2025).
cancer (continued). "This study, therefore, highlights the therapeutic potential of manipulating NINJ1 to regulate ferroptosis as a strategy for cancer treatment." (PMID 40075648, 2025). "By bridging insights from basic research to clinical application, NINJ1-targeted therapies can potentially transform treatment paradigms for cancer and inflammatory diseases, offering hope for improved patient outcomes." (PMID 40075648, 2025). "This suggests a potential role for NINJ1 in enhancing ferroptosis in these cancer types, consistent with our observation that NINJ1 knockdown protects PC3 cells against erastin-induced ferroptosis." (PMID 39424803, 2024). "We then wish to determine the potential in vivo relevance between NINJ1 and ferroptosis in human cancer." (PMID 39424803, 2024). "NINJ1 knockdown significantly protected cancer cells against ferroptosis induced only by xCT inhibitors but no other classes of ferroptosis-inducing compounds (FINs)." (PMID 39424803, 2024). "In this study, we systemically examined the role of NINJ1 in the ferroptosis of cancer cells induced by various FINs." (PMID 39424803, 2024). "Our study predominantly focuses on unraveling the involvement of NINJ1 in ferroptosis in cancer, presenting a model that deviates from the traditional role of NINJ1 in mediating PMR during lytic cell death." (PMID 39424803, 2024). "NGS sequencing confirmed the efficient deletion of Ninj1 gene in each cancer cell line transduced with a Ninj1 specific sgRNA." (PMID 36739334, 2023). "Hence, Ninj1 may be implicated in the development and progression of various human cancers." (PMID 35395804, 2022). "Given the context- and tumor-specific role of NINJ1, NINJ1 activators could be used to target cancer cells resistant to ferroptosis while minimizing damage to normal tissues." (PMID 40075648, 2025). "By regulating xCT stability and ferroptosis sensitivity, combining xCT inhibitors with NINJ1 activation could provide therapeutic benefits in cancers highly dependent on xCT for survival." (PMID 40075648, 2025). "However, the mechanism by which NINJ1 functions in tumorigenesis, metastasis, and cancer progression remains not fully understood." (PMID 39958360, 2025). "Understanding the dual role of NINJ1 in promoting or restraining ferroptosis depending on cellular context could open avenues for novel anti-cancer strategies to enhance ferroptotic vulnerability in metastatic tumors." (PMID 40075648, 2025). "Consequently, NINJ1 has been suggested as a biomarker and a therapeutic target in multiple human cancers." (PMID 39424803, 2024). "Therefore, Ninj1-targeting therapeutics can be combined with other anticancer drugs to treat diverse human cancers." (PMID 35395804, 2022). "Additionally, Ninj1 is overexpressed in various cancers, including hepatocellular carcinoma, acute lymphoblastic B-cell leukemia, urothelial bladder cancer, and circulating prostate cancer cells." (PMID 35395804, 2022). "Public data analysis revealed that NINJ1 expression was a poor prognostic factor in these cancers." (PMID 35395804, 2022). "Conversely, NINJ1 inhibitors could be applied in cancer cells that rely on NINJ1 for proliferation." (PMID 40075648, 2025). "Therefore, it is conceivable that NINJ1 may assume a distinct or additional role in ferroptosis within the context of cancer." (PMID 39424803, 2024).
cancer (continued). "Additionally, while our research centers on cancer cells, since previous studies on NINJ1 were mainly performed in macrophages, especially in BMDMs, it will be valuable to further validate our results using BMDMs with NINJ1 knockout." (PMID 39424803, 2024). "Ninj1 expression is induced in response to various stresses within the tumor microenvironment (TME) and plays an important role in macrophage-mediated inflammation and vascular remodeling, both of which have been closely implicated in cancer development and progression." (PMID 35395804, 2022). "This review synthesizes current knowledge regarding the structural basis and mechanism of NINJ1-mediated PMR and discusses its significance and therapeutic targeting potential in inflammatory diseases, neurological disorders, cancer, and vascular injuries." (PMID 39958360, 2025). "Positive correlations between the expression levels of NINJ1 and SOX2 were observed in these cancers." (PMID 35395804, 2022). "While both NINJ1 and NINJ2 are found to be over-expressed in several types of cancers, it remains unclear whether they can be targeted for cancer treatment." (PMID 40136650, 2025). "Thus, our study has laid a foundation for developing peptide-based strategies to target NINJ1 and NINJ2 for cancer therapy." (PMID 40136650, 2025). "We found that NINJ1 expression was upregulated in a publicly available dataset from cancer cells subjected to hyperthermia (GSE4839845), providing further evidence that NINJ1 may play a role in the HS response." (PMID 38409108, 2024). "Importantly, the enhanced xCT expression was consistently observed across various cancer cell lines, including MCF7, T47D, CAOV3, and PC3 cell lines, highlighting the broad impact of NINJ1 knockdown." (PMID 39424803, 2024). "Collectively, these results suggest that NINJ1 knockdown specifically protects cancer cells against class I FINs, but not other classes of FINs." (PMID 39424803, 2024). "Notably, the reduction in cell lysis due to NINJ1 deficiency was significant only in BMDMs and MEFs, with the minimal effect observed in RAW 264.7 cells, indicating a cell type-dependent role of NINJ1 in ferroptosis that may vary between normal and cancer cells." (PMID 39424803, 2024). "Cell viability assays revealed that the removal of NINJ1 did not have marked impact on APR-246 induced killing but significantly reduced the release of LDH in both the parental cancer cells and their BAX/BAK double knockout derivatives." (PMID 36739334, 2023). "While we were able to reproduce the finding that NINJ1 knockdown did not affect RSL3-induced ferroptosis, we found that NINJ1 knockdown robustly protected cancer cells against ferroptosis induced by xCT inhibitors, such as erastin and SAS." (PMID 39424803, 2024).
tumor (12 papers, 2020 to 2025). "In some studies, elevated NINJ1 levels have been linked to increased tumor progression and mobility, while others indicate that NINJ1 overexpression can suppress tumor growth." (PMID 40075648, 2025). "Among the six model genes, ASPH, CDKN2A, and NINJ1 exhibited strong correlations with tumor-associated immune cells." (PMID 39980566, 2025). "NINJ1 downregulation has been associated with tumor recurrence, treatment resistance, and poorer survival in ovarian cancer patients." (PMID 40075648, 2025). "An associated elevation in Ninj1 and Nanog expression was also observed in tumor nodules in Scgb1a1-CreERTM;L-Ninj1Tg/+ and Sftpc-CreERT2;L-Ninj1Tg/+;KrasG12D/+ mice." (PMID 35395804, 2022). "Some studies associate elevated NINJ1 levels with enhanced tumor progression and mobility." (PMID 39424803, 2024). "First, as a mediator of PMR, NINJ1 inhibition can reduce the release of pro-inflammatory DAMPs, potentially mitigating chronic inflammation and tumor progression." (PMID 40075648, 2025). "This review explores the role of NINJ1 in tumor invasion and metastasis, focusing on its regulation of ferroptosis via a non-canonical mechanism distinct from other cell deaths." (PMID 40075648, 2025). "The indication is that CDKN2A and NINJ1 potentially impact tumor prognosis by regulating the infiltration of immune cells." (PMID 39980566, 2025). "Other research suggests that NINJ1 overexpression suppresses tumor growth and its expression is downregulated during tumor recurrence and treatment resistance." (PMID 39424803, 2024). "To evaluate the impact of Ninj1 expression on the functions of PCs/VSMCs during wound healing, we induced Ninj1 gene silencing in NG2+cells (Ninj1 knockout [KO]) using tamoxifen (Tam) treatment before inflicting skin injury in the NG2CreER:Ninj1loxP mice." (PMID 36262667, 2022). "Our results suggest that Ninj1 is a potential target for anti-CSC strategies to suppress tumor growth and overcome anticancer drug resistance in patients with NSCLC." (PMID 35395804, 2022). "Several lines of evidence suggest the involvement of Ninj1 in the endothelial cell and monocyte adhesion during tumor infiltration." (PMID 32353975, 2020). "We initially expected that the induction of Ninj1 by the radiation would improve the tumor infiltration of macrophage." (PMID 32353975, 2020). "NINJ1 plays a pivotal role in cell motility by mediating cell–cell adhesion through homophilic binding and facilitating immune cell infiltration, thereby influencing tumor proliferation, metastasis, and microenvironment." (PMID 40075648, 2025). "Additionally, it highlights the therapeutic potential of activating or inhibiting NINJ1 to affect tumor growth and ferroptosis sensitivity, a key tumor-suppressing mechanism." (PMID 40075648, 2025).
tumor (continued). "Fourth, in metastatic settings, strategies aimed at inhibiting NINJ1-mediated motility and adhesion offer a potential strategy to prevent tumor dissemination while sensitizing tumor cells to ferroptosis-inducing agents or other pro-ferroptosis conditions in the bloodstream." (PMID 40075648, 2025). "Moreover, due to its adhesion properties, NINJ1 is effective in facilitating tumor metastasis in multiple tumor types." (PMID 39958360, 2025). "In conclusion, NINJ1 is a critical node linking ferroptosis, inflammation, tumor progression, and metastasis, providing a unique therapeutic opportunity to inhibit or treat tumor metastasis." (PMID 40075648, 2025). "In this context, various approaches for activating NINJ1 may have the potential to enhance ferroptosis and sensitize tumor cells to ferroptosis-inducing therapies." (PMID 39424803, 2024). "Taken together, the results of the present investigation support the hypothesis that Ninj1 produced by endothelial cells may be deeply involved in tumor radiotherapy resistance." (PMID 32353975, 2020). "Similarly, in the colitis-mediated colon cancer mouse model, NINJ1 decreases macrophage migration into the tumor sites, thereby reducing macrophage infiltration and suppressing angiogenesis in the tumor mass, resulting in the development of fewer and smaller tumors." (PMID 39958360, 2025). "However, the role of Ninj1 in neoplasia is controversial, as it is known to exhibit both tumor-promoting and tumor-inhibiting activities, and its mechanism of action is largely unknown." (PMID 35395804, 2022). "Three recent papers have mentioned the potential role of NINJ1 in ferroptosis across different cell types, including mouse BMDMs, MEFs, and RAW 264.7 cells (a macrophage cell line derived from an Abelson murine leukemia virus-induced tumor)." (PMID 39424803, 2024). "In lung cancer, inhibiting NINJ1 significantly increased the expression and secretion of IL-6, enhanced cell migration, and ultimately induced a significant increase in the incidence of lung metastasis, as well as the sizes and number of tumor nodules, without affecting tumor growth." (PMID 39958360, 2025).
inflammation (5 papers, 2018 to 2026). Aberrant reaction of the microcirculation characterized by movement of fluid and leukocytes from the blood into extravascular tissues. "Once again, these results suggested that Ninj1 would play an important role in developing pulmonary inflammation and fibrosis induced by BLM." (PMID 30510259, 2018). "The soluble MMP-9-cleaved ectodomain of NINJ1 (sNINJ1) exerts anti-inflammatory and atheroprotective effects, creating a functional paradox in which a single protein can both promote and restrain cardiovascular inflammation." (PMID 41841425, 2026). "Considering the pathogenesis of LPS/D‐gal‐induced liver inflammation and our in vitro experiment data, we hypothesized that Ninj1 in hepatocytes plays a crucial role in the pathogenesis of LPS/D‐gal‐induced ALF." (PMID 36071453, 2022).